FOXP3 (forkhead box P3)
Diseases named in the same sentence as FOXP3 in open-access papers (continued):
Sharing a sentence is not in itself a finding about the gene and the disease.
gastric cancer (continued). "Here, our data confirms CD163 in gastric cancer has a positive correlation with Tregs (CD4, CD25 and FOXP3), MDSCs (CD33, CD11b and CD14) and Cafs (FAP), indicating CD163 level is an potential index to monitor the status of tumor associated macrophages, Tregs, MDSCs and Cafs in gastric cancer." (PMID 29152078, 2017). "Moreover, HLA-G associated immune escape in gastric cancer might be mediated by suppressing CD8+ T lymphocytes and increasing local Foxp3+ regulatory T (Treg) cells." (PMID 26627200, 2015). "Therefore, our study demonstrated that both high CCR7 expression and increased intratumoral FOXP3+ Tregs could be considered as an indicator of poor prognosis in gastric cancer." (PMID 24040244, 2013). "Thus, the presence of H. pylori infection may lead to complications in the evaluation of Foxp3+ T regs in tumoral immunity of gastric cancer." (PMID 18087278, 2008). "It is possible to presume that a tumour-related factor may induce an accumulation of Foxp3+ T regs in the peri-tumoral region at the early stage of gastric cancer, since stage I patients with a peri-tumoral localisation pattern were significantly more frequent." (PMID 18087278, 2008). "This combined therapy downregulates Foxp3, IL-10, and TGF-β1 expression, reduces Treg proportions in peripheral blood, and modulates the immunosuppressive microenvironment of gastric cancer." (PMID 41438510, 2025). "In a study of HIF-1α and the Treg surface marker Foxp3 in gastric cancer, expression of HIF-1α and Foxp3 was found to be positively correlated with tumor stage and degree of peripheral lymph node metastasis." (PMID 40216744, 2025). "Tα1 increased the percentage of CD4+CD25+Foxp3+ (suppressive antitumor-specific Tregs), Tregs, IL-1β, TNF-α, and IL-6 in patients with gastric carcinoma." (PMID 40599771, 2025). "Foxp3 interacts to the PSMD7 promoter and stimulates PSMD7 expression, both of which are up-regulated in gastric cancer tissues, boosting GC cell proliferation and blocking apoptosis." (PMID 38919615, 2024). "miR-133a-3p inhibits Foxp3 expression by binding to Foxp3 3′ UTR, thereby promoting proliferation and autophagy in gastric cancer cells." (PMID 38632598, 2024). "Researchers found a favorable prognostic role for HEVs in gastric cancer by analyzing the combination of CD8+ and Foxp3+ TILs with HEVs." (PMID 39840050, 2024). "detected different T cell subtypes and their relationship with survival times in gastric cancer tissue with multiple fluorescence, and found that CD45RO-cell and FOXP3-cell densities were significantly related to tumor-specific survival." (PMID 36891293, 2023). "CD8+FoxP3+ Tregs have a suppressive role in different types of cancers such as prostate, colorectal, hepatic and gastric cancers, similar to CD4+FoxP3+ T cells." (PMID 35804964, 2022). "For example, Stenoprophomonas and Selenomonas are increased in gastric cancer and positively correlated with BDCA2 + pDCs and Foxp3 + Tregs, while Comannas and Gailla are negatively correlated with BDCA2 + pDCs and Foxp3 + Tregs." (PMID 35093110, 2022). "In this study, we aimed to explore the role of PSMD7 in gastric cancer cells and the combination between PSMD7 and FOXP3." (PMID 35037550, 2022). "In patients with advanced gastric cancers, CD45RA- FoxP3+ CD4+ effector Tregs cells expressing VEGFR-2 are present in higher frequency in TIL than in PBMC." (PMID 33854498, 2021). "In addition, Treg diversity may also partially explain why Tregs have a controversial role in some other malignancies, including gastric cancer, and it may also contribute to the discrepancies between immunohistochemical studies on the role of FoxP3+ Tregs in CM." (PMID 34051744, 2021). "TMA sections were developed to visualize CD3, CD4, CD8, FOXP3, GARP, and CK simultaneously on a cohort of gastric cancer samples." (PMID 34421887, 2021).
gastric cancer (continued). "The regulation of EMT by the Wnt signaling pathway has been determined including Wnt5a, FOXP3, SERPINH1, CUL4B, and SUFU, which can be used in BLCA, gastric cancer, and pancreatic cancer." (PMID 34579753, 2021). "The number and proportion of T lymphocyte in gastric cancer specimens was assessed using three markers: CD3, marking the entire T cell population; CD8, marking the killer/effector T cells; and FOXP3, marking the regulatory T lymphocytes." (PMID 32954467, 2021). "In gastric cancer, previous studies have also demonstrated the prognostic impact of immune cells, such as CD3+, CD8+, Foxp3, and CD45RO cells." (PMID 34987582, 2021). "For survival analyses, the gastric cancer tumors were divided into four quartiles depending on the number CD3+, CD8+, and FOXP3+ T lymphocytes." (PMID 32954467, 2021). "Foxp3+ and CD4+ T cell counts were also increased in gastric cancer in CVID patients (p = 0.001; p = 0.003), in this case in keeping with the results obtained in the whole series (Section 3.3)." (PMID 32575504, 2020). "We confirmed that the expression levels of peripheral and tumor‐infiltrating DC2s, CD4+/CD8 + T cells, Foxp3 + Tregs, and IDO were correlated with each other as well as with clinicopathological characters and gastric cancer prognosis." (PMID 31631566, 2019). "In another study on patients with gastric cancer and esophageal cancer, a correlation between percentage of Tregs (CD4+ CD25high with Foxp3 mRNA) with the severity of disease was observed in both cancers." (PMID 27866241, 2017). "Bregs were shown to play an immunosuppressive role in gastric cancer by inhibiting Th cytokine production, but also by converting CD4+CD25– effector T cells to CD4+Foxp3+ Tregs in a TGF-β1-dependent way." (PMID 28470464, 2017). "However, a few cases with lower responses also had high levels PD-L1 expression, suggesting that using the CD8+T:Foxp3 and CD8+T:PD-L1 ratios to define 6–7 clusters to separate gastric cancer patients into different risk subgroups may be useful for predicting and guiding PD-L1 therapy." (PMID 29025424, 2017). "We investigated the frequencies of TILs including CD8+ T cells, CD45+CD4+CD25± FOXP3+ Tregs, CD45+CD11b+ CD14+ HLA−DR− MDSCs in 28 gastric cancer tissues by using multicolor flow cytometry." (PMID 26799288, 2016). "Actually, it has been reported that FOXP3 expression appears widespread in normal epithelia and malignant cells, such as glioblastoma, ovarian cancer, NSCLC, or advanced gastric cancer." (PMID 24938080, 2014). "After histological confirmation of gastric cancer (upper-left and down-left), we investigated the expression of HIF-1α and Foxp3 by immunohistochemistry in 99 patients." (PMID 23723999, 2013). "Similar results were seen in a gastric cancer model, in which elevated levels of CCL17 and CCL26 in the tumor microenvironment demonstrated a positive correlation with the frequency of Foxp3 Treg, which can bind both these ligands with its CCR4 receptor." (PMID 22112546, 2011). "In the present study, we preferentially described the immunologic nature of the SLN by determining the density of CD8+, FOXP3+, CD57+, or DC-LAMP+ immune cells in gastric cancer." (PMID 21730981, 2011). "Foxp3 showed a positive correlation with IL-10 and TGF-β1 (r ≈ 0.5), suggesting that these immune-suppressive molecules exhibit consistent expression patterns and collectively influence the immune microenvironment in gastric cancer." (PMID 41438510, 2025). "Both HIF-1α and Foxp3 levels were higher in advanced metastatic gastric cancer tissues than in nonmetastatic gastric cancer tissues." (PMID 40216744, 2025). "In gastric cancer, both the MKL1/miR-34a/FOXP3 axis and miR-133a-3p suppress FOXP3 expression." (PMID 41221298, 2025).
gastric cancer (continued). "Two TMA slides, each containing 90 pairs of gastric cancer and corresponding paracancerous tissues, were selected for mIF analysis of TOB1, CD8, CD4, FOXP3, CD20, CD68, and CD66b to investigate the profiles of TOB1 protein expression and immune cell infiltration in gastric cancer." (PMID 38617839, 2024). "Neoadjuvant chemotherapy in gastric cancer patients induced dynamic changes in infiltration of CD8 + T cells and total macrophages, with high-density infiltration of FoxP3 + Tregs in the stromal region before treatment being associated with treatment non-response." (PMID 38802821, 2024). "Meanwhile, Foxp3 reduces COX2 expression and cell metastasis as a negative regulator of NF-ƘB activity, presenting new therapeutic and diagnostic alternatives for gastric cancer." (PMID 38919615, 2024). "Comparing gene expression in 32 pairs of cancerous and noncancerous tissues from gastric cancer patients in TCGA database revealed that FOXP3 expression was significantly upregulated in tumor samples compared with that in matched normal samples." (PMID 37208608, 2023). "The correlation analysis between Treg cell signature genes (CD4, CD25 and FOXP3) and CD8A in The Cancer Genome Atlas (TCGA) database containing 415 gastric cancer samples revealed that the expression of CD4, CD25 and FOXP3 was positively correlated with CD8A expression respectively." (PMID 37208608, 2023). "Proteasome 26S non-ATPase subunit 7 (PSMD7) and forkhead box P3 (FOXP3) have been found to be both upregulated in gastric cancer tissues." (PMID 35037550, 2022). "In conclusion, this study established that PSMD7 could be transcriptionally activated by FOXP3 in HGC-27 cells and facilitate cell proliferation and inhibit cell apoptosis in gastric cancer." (PMID 35037550, 2022). "We matched eight H. pylori-positive, APCA-negative patients to eight pure AIG patients by propensity scoring; we investigated mucin type, PD-L1 expression, infiltration of CD3/CD11b/Foxp3/PD1-positive cells, and bacteria in gastric cancer regions by immunohistochemical staining." (PMID 35453635, 2022). "In the case of dCCA, the tumor immune microenvironment is less complicated than other tumor types, such as head and neck cancer, gastric cancer, and others, as we only defined cytotoxic CD8+ T cells as effector T cells as well as FOXP3+ Treg cells as immune tolerance cells." (PMID 35219893, 2022). "Firstly, we explore the role of FOXP3-mediated PSMD7 in proliferation and apoptosis in gastric cancer cells, but more functional experiments should be assessed to widely investigate the role of PSMD7 in gastric cancer." (PMID 35037550, 2022). "The results demonstrate that the immune suppressive gene FOXP3 and IL-10 were highly expressed in CD8+ T cells after exposed to exosomes from gastric cancer cells, which suggest that exosomes from gastric cancer are required to promote an immunosuppresive phenotype." (PMID 32901082, 2020). "In the entire cohort, CD20+ B cells correlated strongly, and IGKC+ plasma cells correlated moderately to strongly, with CD3+, CD8+ and FoxP3+ cells respectively, with similar findings in esophageal and gastric cancer for CD20+ cells and stronger correlations for IGKC+ plasma cells in gastric cancer." (PMID 29069772, 2017). "Furthermore, CD24hiCD38hiBregs convert CD4+CD25− effector T cells into CD4+FoxP3+ Tregs, which are dependent on TGF-β1 in gastric cancer." (PMID 26378021, 2015). "Moreover, Bregs play a significant immunosuppressive role in gastric cancer, not only by inhibiting CD4+Th cell cytokine production, but also by converting CD4+CD25− effector T cells to CD4+FoxP3+Tregs in a TGF-β1- dependent way." (PMID 26378021, 2015). "Next, the expressions of HIF-1α and Foxp3 in tumor tissues were compared in patients with nonmetastatic (n = 52) and metastatic (n = 47) gastric cancer." (PMID 23723999, 2013).
gastric cancer (continued). "Here, we investigated the density of CD8+, FOXP3+, CD57+, and DC-LAMP+ immune cells in the SLN and found that the density of FOXP3+ regulatory T cell (Treg) is an independent predictive factor of non-SLN metastasis in gastric cancer." (PMID 21730981, 2011). "In a Chinese study involving tumor, peritumor and normal tissues extracted from 60 gastric cancer patients without preoperative chemotherapy, Gaiella was found to be inversely correlated with gastric Foxp3 + Treg, which are increased in tumoral and peritumoral tissues compared to normal ones." (PMID 40153368, 2025). "Using the paraffin slides of gastric cancer, no significant changes were noted in the ratio of Foxp3+ Tregs in the tumor when Gan mice were fed a high-fat diet with GO-Y022 (number of Tregs in the tumor: control mice = 2.34 ± 2.65/mm2, GO-Y022-treated mice = 2.20 ± 2.47/mm2, p-value = 0.9487)." (PMID 36814928, 2023). "Greater infiltration of CD3-positive (p = 0.001), Foxp3-positive (p < 0.001), and PD1-positive cells (p = 0.001); lesser infiltration of CD11b-positive (p = 0.005) cells; and a higher prevalence of Bacillus cereus (p = 0.006) were found in AIG-related gastric cancer patients." (PMID 35453635, 2022). "Moreover, the MC2 group of MCs could promote the recruitment of regulatory T cells (Tregs), since some studies have demonstrated that tryptase, a classical marker of MCs, has a positive correlation with the Treg marker FOXP3 in human gastric cancer (GC) and hepatocellular carcinoma." (PMID 35159157, 2022). "Analysis of more than 1000 gastric cancer samples demonstrated that in comparison with Asian tumors, non-Asian gastric cancers had higher expression of T cell markers (CD3, CD45R0, and CD8), including CTLA-4 signaling and lower expression of the immunosuppressive T regulatory cell marker FOXP3." (PMID 35205802, 2022). "Furthermore, the ratio of cytotoxic T cells to regulatory T cells (CD8+:Foxp3+), and cytotoxic T cells to PD‐L1 (CD8+:PD‐L1+) were also found to be suppressed in the microenvironment of gastric cancer tissues compared to those of normal adjacent gastric tissues." (PMID 33072322, 2020). "Through further univariate analysis of tumoral PD-L1 status combined with each line of TILs, tumoral PD-L1(+)/FOXP3+/low TILs revealed a worse clinical outcome; however, tumor stage (pTNM) was the only independent prognostic factor in EBV-positive gastric carcinomas." (PMID 32498695, 2020). "Immunocompetent cells and humoral immune factors, including DC2s, CD4+/CD8 + T cells, Foxp3 + Tregs, and IDO, interact with each other to compose a complex community of tumor immune microenvironment, ultimately affecting tumor progression and survival of gastric cancer." (PMID 31631566, 2019). "In tissue microarrays of gastric cancers collected from 133 patients, which have been shown to be a powerful tool for evaluating tumor specimens, we used an immunohistochemical method to examine the expression levels of CCR7 and FOXP3 in gastric cancer tissues." (PMID 24040244, 2013). "FOXP3+ non-Treg are considered immunostimulatory and may account for the reported association between increased FOXP3+ TIL and improved prognosis reported for certain cancers such as colorectal and gastric cancer." (PMID 33013886, 2020). "To demonstrate our hypothesis, we analyzed the expression of hypoxia inducible factor-1α (HIF-1α) and Foxp3 in gastric cancer tissues, assessed the effect of hypoxia on TGF-β1 production in cancer cell lines, and finally elucidated the role of hypoxia mediating Treg enrichment in gastric cancer." (PMID 23723999, 2013). "Accordingly, elevated levels of long intergenic noncoding RNA POU3F3 (linc-POU3F3) in gastric cancer (GC) patient-derived Tregs augments Treg distribution, through modulation of TGF-β signaling pathway, while lncRNA Flatr enhances the immunosuppressive function of Tregs by boosting FOXP3 expression." (PMID 34943820, 2021).
gastric cancer (continued). "In non-neoplastic mucosa distant from gastric cancer, CVID cases harboured higher Foxp3+, GATA3+ and PD-L1+ intraepithelial lymphocytes (p < 0.001; p = 0.014; p = 0.011)." (PMID 32575504, 2020). "In non-CVID patients, there was an increase of Foxp3+, GATA3+, CD4+ and CD8+ T cell counts as well CD20+ B cell counts when the non-neoplastic mucosa distant from tumour was compared to gastric cancer (p = 0.001; p = 0.002; p = 0.006; p = 0.003; p = 0.004, respectively)." (PMID 32575504, 2020). "For instance, in gastric cancer, non-Asian patients show significantly higher expression level of T-cell markers, including CD3 and CD8, and lower expression level of immunosuppressive T-regulatory cell markers, such as FOXP3 compared to Asian gastric patients." (PMID 28453554, 2017).